ALK (ALK receptor tyrosine kinase)
Diseases named in the same sentence as ALK in open-access papers (continued):
Sharing a sentence is not in itself a finding about the gene and the disease.
lung cancer (continued). "Lorlatinib, an orally administered inhibitor of anaplastic lymphoma kinase (ALK) and ROS1, was administered in patients with ALK rearrangement pursuant to the findings observed in lung cancer." (PMID 35953681, 2023). "Historically, FISH has been used to identify gene fusion detection in clinical practice, as in the identification of ALK, ROS1, and RET rearrangements in lung cancer." (PMID 37143440, 2023). "Although ALK‐positive NSCLC patients represent a small percentage of all NSCLC cases, they contribute significantly to the overall number of lung cancer cases worldwide." (PMID 38077251, 2023). "Treatment of lung cancer cells with inhibitors of KRAS, EGFR or ALK results in caspase-3-regulated activation of GSDME, thereby increasing the anticancer efficacy of these drugs." (PMID 36920176, 2023). "MS4077 and MS4078 potently reduced the levels of oncogenic active ALK fusion proteins and inhibited ALK and STAT3 phosphorylation in SU-DHL-1 lymphoma and NCI-H2228 lung cancer cells." (PMID 36986673, 2023). "Consistently, Clinical drugs targeting ALK, such as alectinib and lorlatinib, have been found to inhibit cellular EMT signalling in lung cancer." (PMID 36808651, 2023). "Anaplastic lymphoma kinase (ALK) is an RTK and an oncogenic driver in non–small-cell lung cancer (NSCLC), anaplastic large-cell lymphoma, and IMT, among other tumors." (PMID 38096470, 2023). "In this study, we revealed a novel mechanism of adaptive resistance to the third generation ALK-TKI, lorlatinib, in ALK-rearranged lung cancer." (PMID 36702855, 2023). "The subsequent systematic review focuses on the utilization of LCOs as in vitro models to assess drug sensitivity, encompassing chemotherapeutic agents and targeted drugs against common lung cancer biomarkers such as EFGR, ALK, and KRAS." (PMID 37941550, 2023). "Due to its high activity in lung cancers with ALK or ROS1 chromosomal rearrangements, crizotinib, the first-generation ALK tyrosine kinase inhibitor (TKI), is now widely used in clincal practice." (PMID 37036582, 2023). "Common targeted therapies for lung cancer include EGFR inhibitors, such as Erlotinib and Afatinib, and ALK inhibitors, such as Crizotinib and Alectinib." (PMID 38026900, 2023). "In lung cancer, two f-circRNAs derived from EML4::ALK fusion have been identified, and proposed as a liquid biopsy biomarker, whereas another f-circRNA from SLC34A2::ROS1 translocation was proven to boost cancer cell migration." (PMID 36585787, 2023). "Small molecule inhibitors are available for treating ALK, ROS1, RET and NTRK1-rearranged receptor tyrosine kinases (RTKs) in lung cancers, but variable or incomplete responses are often observed and acquired resistance is unavoidable." (PMID 37470475, 2023). "Anaplastic lymphoma kinase (ALK), epidermal growth factor receptor (EGFR), c-ros Repressor of Silencing 1 (ROS1) as crucial lung cancer gene targets have been unanimously recognized by today academic circles, and the era of targeted therapy has begun." (PMID 35313900, 2022). "Of the 31 ALK fusion events detected in non-lung cancers, including gastrointestinal and gynecological cancers, 11 patients (35.5%) were detected with EML4-ALK fusions." (PMID 36369474, 2022). "Small molecule inhibitors of kinases such as MEK, BRAF, EGFR, ALK, and KRAS promoted GSDME cleavage by CASP3 and resulted in lung cancer and melanoma regression." (PMID 35964070, 2022). "As sporadic cases of TKI-addicted ALK-altered lung cancers are in the NET/NEC population, selected patients fit enough for advanced line therapy, should be tested for the presence of ALK protein." (PMID 35677534, 2022). "KRAS mutations are mutually exclusive with alterations in other molecular markers such as EGFR, ALK and ROS1, considered genetic drivers of lung cancer development." (PMID 36077640, 2022).
lung cancer (continued). "In addition, fusions in ALK (overall, Fisher’s exact test P < 0.0001; lung cancer, P < 0.0001), ROS1 (overall, Fisher’s exact test P < 0.0001; lung cancer, P < 0.0001) and RET (overall, Fisher’s exact test P = 0.006; lung cancer, P < 0.0001) were associated with an earlier disease onset." (PMID 36369474, 2022). "Several driver genes have been identified in lung cancer, such as epidermal growth factor receptor (EGFR), anaplastic lymphoma kinase (ALK), and Kirsten rat sarcoma virus oncogene homolog (KRAS)." (PMID 35582531, 2022). "We then used the same method to verify the relationship between GILncSig and lung cancer driver genes (EGFR and ALK) and obtained similar conclusions." (PMID 35372012, 2022). "Sequentially, we evaluated the targetable variations detected ability in different samples, including EGFR, ALK, BRAF V600E, KRAS, MET ex14 skipping, RET, ROS1, ERBB2, which have high evidence in lung cancer." (PMID 36167530, 2022). "We found eight genes relevant to lung cancer (PDGFRB, RET, KRAS, KEAP1, ROS1, STK11, MET and ALK), for which integrating clinical data with our TME features clearly improves the ability to predict mutations in these genes." (PMID 36131239, 2022). "On the other hand, similar to ALK and ROS1 fusion-positive lung cancers, patients with NTRK fusion also can develop off-target resistance to TKI therapy, mechanisms including MET amplification, BRAF V600E mutation, or hotspot mutations involving KRAS." (PMID 36508072, 2022). "The positive rate of ROS1 gene fusion in NSCLC was 1.0%–3.4%,31 and the clinical characteristics of ALK and ROS1 gene fusion lung cancer were also very similar." (PMID 35081265, 2022). "Our study extended the spectrum of ALK fusion partners in ALK + NSCLC, and we reported a new ALK fusion: ALK-GCA and EML4-ALK and its sensitivity to alectinib firstly in lung cancer." (PMID 35070986, 2022). "To examine the roles of STAT3 in acquired resistance of ALK-rearranged lung cancer, we evaluated STAT3 activity and effects of the combined treatment on acquired resistant ALK-rearranged cells." (PMID 35228642, 2022). "In the past decade, advances in epidermal growth factor receptor (EGFR) therapy and anaplastic lymphoma kinase (ALK) therapy have remarkably improved the survival of EGFR positive and ALK positive lung cancer patients." (PMID 35971127, 2022). "A previous study in 36,813 Chinese lung cancer patients, focusing on eight key lung cancer driver genes (EGFR, ALK, MET, KRAS, ERBB2, ROS1, RET, and BRAF), revealed a prevalence of 0.03% for P/LP germline mutations." (PMID 35428225, 2022). "Although GEM models for EML4‐ALK lung cancer were first established in 2008, the use of GEM models to assess the in vivo potency of ALK TKIs was limited due to technical challenges." (PMID 34845836, 2022). "Considering our findings, a clinical trial is warranted to assess the efficacy of the new combination therapy co-targeting ALK and STAT3 in ALK-rearranged lung cancer." (PMID 35228642, 2022). "Based on the results of KEYNOTE-158 clinical trial, pembrolizumab has been approved by FDA as the front-line therapy for advanced lung cancer patients who present high PD-L1 expressions (TPS > 50%) and who are diagnosed as EGFR or ALK wild-type." (PMID 35346207, 2022). "The coexistence of ALK, MET, and other alterations has been observed in a series of cases with lung cancer and is reported here in MET-positive ASPS tumors with ALK mutations." (PMID 35628499, 2022). "Examples of these paradigms include EGFR inhibitors in EGFR-mutant non–small cell lung cancer (NSCLC) and ALK inhibitors in ALK-translocated NSCLC." (PMID 36506869, 2022). "After verifying that ALK can enhance the stability of total TOPK, we further explored the effect of TOPK on the phenotype of ALK-positive lung cancer cells." (PMID 36167821, 2022). "Genetic testing for advanced nonsmall cell lung cancer (NSCLC) includes EGFR, ALK, ROS1, BRAF, MET, HER-2, RET, NTRK1/2/3, PI3K, and PD-L1." (PMID 35368895, 2022).
lung cancer (continued). "Although ALK rearrangement occurs in about 5% of NSCLC, it has recently been confirmed to have a powerful transforming effect in lung cancer patients." (PMID 35626451, 2022). "In fact, compared with other targeted therapies (e.g. ALK-TKI and VEGFR), EFGR-TKI treatments result in more severe skin ADRs, which is especially true for lung cancer treatment, in which EGFR-TKIs have been commonly used." (PMID 35505288, 2022). "The third-generation anaplastic lymphoma tyrosine kinase inhibitor (ALK-TKI) lorlatinib has a unique side effect profile that includes hypercholesteremia and hypertriglyceridemia in >80% of lung cancer patients." (PMID 36077379, 2022). "Latest results have shown that around 83% of the lung cancer patients included in the cohort study (n = 2.204) were tested for EGFR, ALK, ROS-1, PD-L1 and / or BRAF." (PMID 35765059, 2022). "Two molecular pathways have been identified as relevant for lung cancer in recent years: the epidermal growth factor receptor (EGFR) and the anaplastic lymphoma kinase (ALK), respectively." (PMID 33777098, 2021). "The advancements in molecular profiling in lung cancer have provided powerful tools for implementing new treatments, such as EGFR and ALK tyrosine kinase inhibitors." (PMID 33956842, 2021). "The first oncogenic fusion detected in lung cancer was EML4–ALK, resulting from a small inversion on the short arm of chromosome 2, that promotes the fusion of EML4 N-terminal with ALK (exon 20)." (PMID 33916986, 2021). "Pulmonary LELC had better prognosis, and previous studies also have discovered that classic lung cancer oncogenic drivers including KRAS, EGFR, BRAF, ALK, and ROS1 were limitedly involved in tumorigenesis and progression of pulmonary LELC." (PMID 34221995, 2021). "In patients in the advanced stages of lung cancer, finding target molecules, such as EGFR, ALK, and ROS1, is significant for making treatment decisions; as such, it is necessary to perform molecular testing at the time of initial diagnosis." (PMID 34441366, 2021). "Especially in the treatment of lung cancer, the main origin of brain metastases, several molecular markers such as EGFR, ALK, or PD1 can be exploited for targeted therapy approaches." (PMID 33883632, 2021). "More importantly, when H2228 cells, an EML4–ALK fusion-containing lung cancer cell line, were immunostained with an anti-ALK antibody, we observed similar spherical condensates, suggesting that endogenous EML4–ALK also undergoes LLPS." (PMID 33976114, 2021). "For lung cancer, we collect the status of the National Comprehensive Cancer Network (NCCN) recommended biomarkers: EGFR, ALK, BRAF, ROS1, KRAS, RET, NTRK and PD-L1." (PMID 33572220, 2021). "Recently, molecular therapeutics targeting receptor tyrosine kinase (RTK) aberrations in lung cancer, including epidermal growth factor receptor (EGFR) and anaplastic lymphoma kinase (ALK), and immunotherapies have been developed." (PMID 33826244, 2021). "Some lung cancer‐related genes, such as EGFR, ALK, and KRAS, are usually used for targeted NGS in early‐stage lung cancer." (PMID 33200540, 2021). "ALK rearrangements result in an oncogenic driver in 5–6% of NSCLC cases, representing approximately 100,000 new cases of lung cancer annually worldwide." (PMID 33806977, 2021). "About 3%‐5% non‐small cell lung cancer (NSCLC) patients carry anaplastic lymphoma kinase (ALK) gene fusions and receive great benefits from ALK‐targeted therapy." (PMID 34766150, 2021). "In most cases, we were able to obtain primary lung cancer samples of sufficient quality using ENB-guided biopsy to perform molecular testing, including EGFR, ALK, and PD-L1." (PMID 34441366, 2021).
lung cancer (continued). "Over the last several decades, clinical evaluation and treatment of lung cancers have largely improved with the classification of genetic drivers of the disease, such as EGFR, ALK, and ROS1." (PMID 33803619, 2021). "Many types of targeted therapies for lung cancer are currently available, such as epidermal growth factor receptor (EFGR) inhibitors (erlotinib and gefitinib) or anaplastic lymphoma kinase (ALK) inhibitors (crizotinib and alectinib)." (PMID 34279440, 2021). "Especially in lung cancer, various targeted therapies have been developed, ranging from EGFR-TKIs and BRAF, ALK, ROS, RET, MET, TRK1, and HER2 inhibitors, to more recent developments in KRAS inhibitors." (PMID 34359729, 2021). "HER2 mutations mainly occur at exon 20 in the protein kinase domain and are recognized as primary drivers in lung cancer, similar to other oncogenic drivers, such as EGFR, ROS, ALK, KRAS and BRAF." (PMID 33959501, 2021). "Nowadays, different classes of ALK tyrosine kinase inhibitors (TKI) are available and used exclusively for EML4-ALK (+) lung cancers." (PMID 33466277, 2021). "A recent prospective multicenter trial presented at the World Conference on Lung Cancer evaluated pembrolizumab and chemotherapy in the setting of recurrent EGFR/ALK-positive NSCLC." (PMID 34926258, 2021). "Lung cancer is the leading cause of cancer-related deaths in the world, and mutations and deregulation of many proteins and pathways, including EGFR, ALK, ROS1, and MET, play a significant role in lung cancer occurrence and development." (PMID 34603447, 2021). "Another study in lung cancer compared the efficacy of crizotinib (ALK inhibitor) against standard-of-care agents, Docetaxel or Pemetrexed, in an EML4-ALK mouse model and Phase III human clinical trials." (PMID 33440754, 2021). "In recent years, many targeted therapies, such as anaplastic lymphoma kinase (ALK), EGFR, ROS1, RET, HER2, and MEK, have become available for advanced lung cancer, and more are in development." (PMID 33573689, 2021). "The majority of lung cancer belongs to NSCLC, where a rearrangement in the ALK gene plays a positive role in 3%-13% of cases." (PMID 33091333, 2021). "Crizotinib and lorlatinib are second‐ and third‐ generation therapeutic inhibitors targeting anaplastic lymphoma kinase (ALK) and are commonly used drugs for the treatment of lung cancer." (PMID 32347012, 2020). "Among those tested, the most common tests administered during baseline were EGFR, molecular cytogenetics (FISH) for ALK or ROS-1, tumor immunochemistry panels (PD-1, PD-L1) and combination lung cancer panels (EGFR, KRAS, ALK, ROS-1, and PD-L1)." (PMID 32187231, 2020). "Other gene targets with genetic alterations in lung cancer include human epidermal growth factor receptor (HER2), Mitogen-activated protein kinase (MEK), Anaplastic lymphoma kinase (ALK), (ROS1) and Fibroblast growth factor receptor 1 (FGFR1)." (PMID 32984047, 2020). "Targeted agents that display activity in treating other lung cancer sub-types (e.g., EGFR- and ALK-inhibitors in NSCLC) are relatively ineffective for SCLC because these pathways are generally not dysregulated in SCLC." (PMID 32224870, 2020). "Specific tests to investigate the presence of ALK, ROS1 and RET rearrangements in lung cancer have been developed by Agena Bioscence." (PMID 32726941, 2020). "Innate immune resistance means that constitutive oncogenic signaling within tumor cells such as ALK-rearranged and EGFR-mutant lung cancer results in the upregulation of PD-L1 expression." (PMID 32325698, 2020). "Published data have shown that epidermal growth factor receptor (EGFR) and anaplastic lymphoma kinase (ALK), molecules for first-line target therapy, improve prognosis for patients with lung cancer." (PMID 32433714, 2020). "Entrectinib received FDA approval for lung cancers harbouring ROS1 alteration in 2019, having demonstrated robust ALK and ROS1 inhibition, plus effective TRKA, TRKB and TRKC signalling suppression." (PMID 33172113, 2020).
lung cancer (continued). "The GSE72526 was a dataset using microRNA to predict ALK, EGFR, and KRAS statuses in lung cancer patients and to use ALK, EGFR, and KRAS as biomarkers to diagnose lung cancer." (PMID 31976313, 2020). "This methodology can detect ALK fusions using different starting material such as FFPE, fresh frozen tissues or lung cancer patient-derived xenograft (PDX)-derived tumors." (PMID 37362555, 2020). "In patients with non–small-cell lung cancer (NSCLC), anaplastic lymphoma kinase (ALK) gene rearrangement is detected in approximately 3–7% of cases." (PMID 32974126, 2020). "As a receptor tyrosine kinase of insulin receptor (IR) subfamily, anaplastic lymphoma kinase (ALK), has been validated to play important roles in various cancers, especially in non–small cell lung cancer (NSCLC) and anaplastic large cell lymphoma (ALCL)." (PMID 33384022, 2020). "Brigatinib, a dual ALK/EGFR inhibitor, is therefore being explored in clinical settings against lymphoma and lung cancer patients (NCT01449461)." (PMID 33262326, 2020). "Later-line lorlatinib treatment can induce sustained responses in patients with advanced ALK- and ROS1-positive lung cancer." (PMID 33171712, 2020). "Here, we performed a retrospective analysis to determine the imaging features and metastatic patterns of advanced RET+ NSCLC, specifically as compared to those of ALK+ and ROS1+ NSCLC, the most common oncogenic fusions in lung cancer." (PMID 32183422, 2020). "The comparator used in this study was crizotinib, at the time the only ALK+ inhibitor approved for first-line treatment of advanced ALK+ NSCLC in France and the recommended first-line treatment for this form of lung cancer in European guidelines." (PMID 31945065, 2020). "A previous study showed that targetable activating alterations in lung cancer genes, such as EGFR, ALK, RET and ROS1, are mutually exclusive molecular events." (PMID 32729257, 2020). "Some excellent examples include genetic tests of the ALK and ROS1 genes performed in lung cancer required for TKI treatment." (PMID 32316657, 2020). "Targeted drugs for lung cancer, mostly NSCLC, mainly include EGFR-tyrosine kinase inhibitors (EGFR-TKIs) and ALK-tyrosine kinase inhibitors (ALK-TKIs)." (PMID 33299643, 2020). "We demonstrated that YAP1 was significantly activated both in vitro and in vivo when ALK-rearranged lung cancer cells were treated with ALC, and the combinatorial inhibition of YAP1 and ALK achieved the suppression of initial survival in vitro and in vivo." (PMID 31900393, 2020). "Co-occurrence of mutation in AGTPBP1 and other altered biomarkers EGFR, KRAS, BRAF, ALK and ROS1 in lung cancer was analyzed." (PMID 33276627, 2020). "Despite recent advances in treating non‐small cell lung cancer (NSCLC) with immune checkpoint inhibitors (ICIs), their role in ALK‐positive NSCLC patients is unclear." (PMID 31509890, 2019). "To investigate the correlation between an EML4-ALK rearrangement and PEM sensitivity, we first evaluated the protein expression of ALK in four lung cancer cell lines by Western blotting." (PMID 31795298, 2019). "The recent identification of driver oncogenes, such as EGFR, ALK, ROS1, and BRAF has already been successfully translated into clinical practice for individuals with lung cancer." (PMID 31142054, 2019). "This is consistent with other studies reporting low TMB in EGFR, ALK, ROS1, or RET-driven lung cancers [30•], but higher in KRAS or BRAF." (PMID 31172347, 2019). "Two phase I study (ALKA-372-001 and STARTRK-1) assessing entrectinib in NTRK-, ROS1-, and ALK-positive solid tumor showed promising efficacy and durable clinical benefit of 32 months in a ROS1-positive lung cancer patients." (PMID 31023335, 2019). "The distinct molecular subtypes of lung cancer are defined by monogenic biomarkers, such as EGFR, KRAS, and ALK rearrangement." (PMID 31480292, 2019). "Crizotinib, an ALK/ROS1/MET inhibitor, is highly effective against ROS1-rearranged lung cancer and is used in clinic." (PMID 31399568, 2019).